BATF2 (basic leucine zipper ATF-like transcription factor 2)
Diseases named in the same sentence as BATF2 in open-access papers (continued):
Sharing a sentence is not in itself a finding about the gene and the disease.
infection (23 papers, 2010 to 2025). The state of being infected such as from the introduction of a foreign agent such as serum, vaccine, antigenic substance or organism. "We currently investigate the consequence of Batf2 deficiency in mice during infection with M. tuberculosis and Listeria monocytogenes." (PMID 26376615, 2015). "Interestingly, we and others showed that loci encoding transcription factors such as Batf2, Fos, and Jun, important in myeloid differentiation were hypermethylated and transcriptionally repressed in Dnmt3a-mutant HSCs after infection." (PMID 40905954, 2025). "The overlap in risk scores in WB and lung tissue observed between the two infection groups in this study indicate that Risk6, Sweeney3, and BATF2 are unable to differentiate between infection doses exceeding 100 CFU, resolving only on exposure to M.tb." (PMID 39651886, 2025). "For Risk6 and Batf2 signatures the lung- and blood-derived scores started to differentiate from baseline around 28 days post-infection." (PMID 39651886, 2025). "Of note, Batf2 was found to be upregulated in all of these infections, suggesting that Batf2 induction differentially regulates immunological response pathways through a feedback mechanism after exposure to infectious agents." (PMID 36672163, 2023). "Upregulation of many genes associated with activation of innate immunity and SARS CoV-2 disease severity were identified during acute (4 dpi) SARS-CoV-2 (Delta variant) infection in cats, such as KIF11, IRF7, OAS1, BATF2, IF16, and BPIFA1." (PMID 35746678, 2022). "Our transcriptome analysis also showed that BATF2 was significantly increased in distinct cell types with IAV stains infection, indicating that it will be increasingly interesting to illustrate the role of BATF2 during IAV infection." (PMID 34367124, 2021). "Basic leucine zipper transcription factor 2 (Batf2) activation is detrimental in Type 1-controlled infectious diseases, demonstrated during infection with Mycobacterium tuberculosis (Mtb) and Listeria monocytogenes Lm." (PMID 30542107, 2019). "Batf2 play regulatory role in CD8α + classical DC development and contributes to anti-T. gondii in vivo infection." (PMID 31333663, 2019). "At 3 weeks post infection, Batf2−/− mice resulted in significantly reduced lung weight index, total lung cell numbers, lung pathology score, as well as histopathology (H&E) in the lungs compared to WT mice." (PMID 30542107, 2019). "Consistent with TB, Lm-infected Batf2−/− mice were also more resistant during high- and low-dose infection with increased survival and reduced bacterial burden in the spleen and liver, compared to WT mice." (PMID 30542107, 2019). "FACS sorting of interstitial recruited macrophages, CD11b+ DC’s and neutrophils (gating strategy) from Mtb-infected wild-type mice showed similar mRNA levels of Batf2 during infection." (PMID 30542107, 2019). "CFU counts were significantly reduced in Batf2−/− when compared to WT mice at 11 days but similar at 3 weeks post-infection." (PMID 30542107, 2019). "Deletion of Batf2 in mice displayed enhanced survival rate when compared to control mice that succumbed to hyper-virulent Mtb (HN878) infection." (PMID 30542107, 2019). "A recent study clearly demonstrated that Batf2 expression induced in Mφs in the lung during infection with M. tuberculosis and Listeria monocytogenes was associated with the pathogenesis of type 1 infectious diseases." (PMID 30753547, 2019). "Strikingly, 71.4% of the control littermates died during the experiment, whereas all infected Batf2−/− mice survived up to 18 weeks post infection." (PMID 30542107, 2019). "Following infection, BATF2 participates in the development of and differentiation of CD8 (+) thymic conventional dendritic cells in the immune system." (PMID 29236770, 2017). "However, R2 values were higher in data sets with lower median days post-infection, particularly for Risk6 and BATF2 signatures." (PMID 39651886, 2025).
infection (continued). "We found that BATF2 was differentially regulated in response to infection in Dnmt3a-KO mice." (PMID 40905954, 2025). "Similarly, Batf2 scores were significantly higher for all of the groups by day 28 when compared with both day 0 and day 14 post-infection (day 0 vs 28 untreated P < 0.0001; RhCMV/TB P < 0.0001; BCG P = 0.0001; BCG + RhCMV/TB P = 0.0006)." (PMID 39651886, 2025). "We found that BATF2 was upregulated during H1N1pdms infection." (PMID 38229736, 2024). "Similarly, infection with Schistosoma mansoni resulted in an aggravated fibro-granulomatous inflammation in Batf2−/− mice compared to the controls." (PMID 36672163, 2023). "Notably, BATF2 was shown to promote inflammation in response to lipopolysaccharides or infection, and LY6E plays a role in T-cell activation and is upregulated by interferons." (PMID 36077244, 2022). "Additionally, Mtb HN878 infection in human monocyte-derived macrophages from healthy donors also showed significant increased BATF2 expression at 48 h post-infection." (PMID 30542107, 2019). "In addition to TB, infection with Listeria monocytogenes (Lm) also resulted in increased Batf2 expression, as a function of time in spleen but transient in liver tissue." (PMID 30542107, 2019). "Importantly, Batf2 was also induced during M. tuberculosis (Mtb, Beijing strain HN878) infection in classical activated macrophages and shRNA-mediated down-regulation of Batf2 resulted in decreased expression Nos2, Tnf, Ccl5 and IL-12b in heat-killed Mtb-stimulated macrophages." (PMID 26376615, 2015). "Accumulating evidence has revealed that the transcription factor BATF2 has unique transcriptional activities, including regulating cytokines via TLR signals in macrophages, which affect mortality due to infection and cancer." (PMID 35246006, 2022). "Only two genes, basic leucine zipper transcription factor, ATF-like 2 (BATF2) and solute carrier family 15, member 3 (SLC15A3) were differentially expressed in response to pdmH1N1 infection only." (PMID 21029402, 2010). "We also transfected the CoV2‐miR‐O7a.2 mimic at a lower concentration to mimic the copy number per cell as observed on the infection (~2,000 copies/cell) (Fig EV5E), and we found that at this concentration as well CoV2‐miR‐O7a.2 is able to downregulate both BATF2 and LAMP3 mRNA (Fig EV5F)." (PMID 34914162, 2022). "This suggest a defect in response to infection rather than just an intrinsic defect as a driver of the observed profile in S. mansoni-infected Batf2−/− mice." (PMID 30542107, 2019). "Of interest, control mice started to die as early as 4 weeks post-infection with a high pulmonary bacterial burden from 1–2 × 109 CFU, whereas Batf2−/− mice at the termination of the experiment had only 2–20 × 105 CFU (3–4 log reduced) pulmonary bacterial burden." (PMID 30542107, 2019). "Moreover, we found that BATF2 could be significantly upregulated with H1N1 and other strain infections in all collected datasets of human primary epithelial cells and endothelial cells, expect one dataset (GSE19392) where the BATF2 gene was not included in the microarray platform." (PMID 34367124, 2021). "Furthermore, we asked whether the absence of Batf2 plays a role in memory to Lm infection, which would rapidly clear infection during the secondary challenge." (PMID 30542107, 2019). "Therefore, we inferred that higher levels of BATF2 may reflect nonspecific host responses to infection, much like the acute-phase reactant, serum C‐reactive protein (CRP) that is widely used as a biomarker for infection and was also not significantly different between the 2 groups." (PMID 27734027, 2016).
cancer (22 papers, 2012 to 2025). A tumor composed of atypical neoplastic, often pleomorphic cells that invade other tissues. "IPA identified cancer among the top associated diseases and the cell cycle as the most highly regulated molecular function of genes bound by BATF2." (PMID 40945729, 2025). "Cancer cells tend to be unstable and have somatic mutations and copy number alterations; therefore, we wondered whether BATF2-regulated PD-L1 expression was mediated by signaling pathway alteration during the unstable process." (PMID 37777155, 2023). "BATF2 has been implicated in the progression and metastasis of diverse cancer in several studies." (PMID 35619651, 2022). "In this work, we sought to explore the expression patterns and diagnostic and prognostic implications of BATF2 mRNA and protein expressions in BC using bioinformatics, which were subsequently verified in the serum, serum-derived exosomes, and cancer tissues of BC patients using qRT-PCR and IHC." (PMID 34565331, 2021). "Some studies have linked BATF2 to the suppression of cell cycle regulation genes, including CCND1, through binding with AP-1 subunits in the context of cancer." (PMID 40945729, 2025). "Mechanically, we showed that BATF2 inhibits programmed death-ligand 1 expression in cancer cells by inhibiting the PI3K–AKT pathway where ZEB2 plays an important role in this process." (PMID 37777155, 2023). "BATF2, one of the transcription factor from basic leucine zipper transcription factor family, has been shown to be related to multiple types of cancers." (PMID 37777155, 2023). "BATF2 belongs to AP‐1 family and interacts mainly with AP‐1 via its bZIP domain in the nucleus, leading to AP‐1 inhibition and cancer suppression." (PMID 37151195, 2023). "BATF2 can express not only on cancer cells but also in immune cell population including T cells, B cells, and other myeloid populations." (PMID 37777155, 2023). "Taken together, the upregulation of BATF2 and the downregulation of both ISG15 and MT2A, as reported here in blood samples from children with ASD, suggesting a reduced risk of cancer." (PMID 36077244, 2022). "Our IHC analysis revealed a positive rate of BATF2 protein expression of 46.90%, mainly located in the nucleus of cancer cells in BC, and the OS of BC patients with high BATF2 protein expressions was prolonged." (PMID 34565331, 2021). "By contrast, BATF2 protein was mainly located in the nucleus of BC cancer cells based on HPA analysis, with a low-to-moderate level in protein expressions in 7 cases out of 12 cases." (PMID 34565331, 2021). "Initially, BATF family members were suggested to be AP-1 inhibitors, but in recent years, oncologists have indicated that BATF2 is also involved in the progression of cancers through diverse mechanisms." (PMID 32650804, 2020). "BATF2 was selected for further experimental validation because BATF2 is involved in the MDR of human cancer." (PMID 32166887, 2020). "Antibodies for Slug, TGFβ1, and basic leucine zipper ATF-like transcription factor 2 (SARI) reacted negatively in all carcinomas." (PMID 29976164, 2018). "Our findings showed that BATF2 inhibits PD-L1 in cancer cells through PI3K–AKT pathway." (PMID 37777155, 2023). "Upregulation of BATF2 and downregulation of ISG15 and MT2A were reported to reduce cancer risk." (PMID 36077244, 2022). "The results showed that BATF2 was mainly expressed in the nucleus of BC cancer cells." (PMID 34565331, 2021). "Therefore, BATF2 has been considered a prognostic indicator and a potential target for gene therapy for various cancers." (PMID 34778372, 2021). "Recent discoveries have indicated the critical roles of BATF2 in the pathogenesis of cancers." (PMID 32650804, 2020). "BATF2 overexpression promotes growth inhibition and apoptosis in cancer cells." (PMID 31174572, 2019). "In cancer, Batf2 could be used as a biomarker for cancer prognosis and a promising therapeutic target against cancer, by augmenting Batf2 in malignant cells." (PMID 26376615, 2015).
cancer (continued). "Thus, synergetic inhibition of CRM1 and induction of BATF2 may provide better solutions for cancer therapy." (PMID 37151195, 2023). "Moreover, Batf2 act as a tumor suppressor gene and augmenting Batf2 in malignant cells might be an encouraging therapeutic treatment against cancer." (PMID 26376615, 2015). "Initially, we examined how BATF2 expression affected survival in GBM patients using the publicly available The Cancer Genome Atlas-GBM dataset and found that higher BATF2 transcript correlated with increased survival." (PMID 40945729, 2025). "The results showed that BATF2 was mainly located in the nucleus of cancer cells of BC, which was consistent with the results of HPA analysis, yet with a lower positive rate of BATF2 protein expression." (PMID 34565331, 2021). "Some studies have confirmed that BATF2 expression is negatively correlated with CCN1 expression and regulates the biological behaviors of cancer cells via regulating CCN1 expression in vivo." (PMID 34565331, 2021). "Besides, BATF2 protein expression (using HPA data) also detectable in cancer cell lines and cancer tissues, which was tested positive in more than 58.33% (7/12) of the BRCA patients in the HPA data." (PMID 34565331, 2021). "The average expression level of BATF2 mRNA in healthy controls was slightly higher than that in BC cancer tissues, but there was no statistical difference." (PMID 34565331, 2021). "Based on UALCAN datasets, high BATF2 expression level and menopause status were indicators of a better prognosis of BRCA patients (cancer type and gender were not significant indicators)." (PMID 34565331, 2021).
infectious disease (4 papers, 2015 to 2019). A disorder directly resulting from the presence and activity of a microbial, viral, or parasitic agent in humans. "In this study, we provide evidence for the regulation of immunity to Type 1 and Type 2 infectious diseases by Batf2." (PMID 30542107, 2019). "Together, these data strongly indicate that Batf2 differentially regulates Type 1 and Type 2 immunity in infectious diseases." (PMID 30542107, 2019). "Several genes involved in the control of infectious diseases such as the Basic leucine zipper ATF transcription factor 2 (BATF2) and the C-X-C motif chemokine ligand 10 (CXCL10), were upregulated in the PB and ICV gene expression profiles from the animal with diffuse lesions." (PMID 31619718, 2019). "Therefore, we compared BATF2 expression levels in the blood transcriptomes of the AdjuVIT cohort active TB cases to those of patients presenting to hospital with febrile illnesses (Fever cohort), representing a diverse spectrum of non‐TB infectious diseases." (PMID 27734027, 2016). "Consistent with our observations in HIV‐1 infection, we found that elevated BATF2 levels were not specific to active TB, but were also variably elevated in HIV-negative patients presenting to hospital with diverse infectious diseases." (PMID 27734027, 2016).
BATF2 also shares sentences with these, for which no sentence is quoted: esophageal squamous cell carcinoma (2 papers); inflammation (2); liver cancer (2); nasopharyngeal carcinoma (2); acute stress disorder (1); anterior uveitis (1); autism (1); autism spectrum disorder (1); bile duct cancer (1); bladder cancer (1); cervical cancer (1); coinfection (1); diabetes (1); fragile X syndrome (1); intestinal schistosomiasis (1); kidney cancer (1); lung adenosquamous carcinoma (1); lung squamous cell carcinoma (1); malaria (1); malignant glioma (1); neuroblastoma (1); pancreatic adenocarcinoma (1); rectal cancer (1); respiratory diseases (1); Respiratory tract infection (1); skin disorder (1); synovial sarcoma (1); tendinitis (1); triple-negative breast carcinoma (1); ulcerative colitis (1).
A further 1 disease shares a sentence with BATF2 in 1 paper.